ADAP2 (ArfGAP with dual PH domains 2)
Description:
GTPase-activating protein for the ADP ribosylation factor family (Potential). Binds phosphatidylinositol 3,4,5-trisphosphate (PtdInsP3) and inositol 1,3,4,5-tetrakisphosphate (InsP4). Possesses a stoichiometry of two binding sites for InsP4 with identical affinity.
Synonyms: CENTA2; HSA272195; cent-b
Tractability: Antibody: UniProt places it where antibodies can reach, with high confidence; its Gene Ontology location is reachable by antibodies, with high confidence.
Gene: Protein-coding gene on chromosome 17 (30,906,344 to 30,959,945, forward strand). Ensembl gene ENSG00000184060.
Subcellular location: Cytoplasm; Cell membrane
Gene Ontology:
Molecular function: inositol 1,3,4,5 tetrakisphosphate binding; phosphatidylinositol-3,4,5-trisphosphate binding; protein binding; GTPase activator activity; phosphatidylinositol-3,4-bisphosphate binding; phosphatidylinositol-4,5-bisphosphate binding; protein-macromolecule adaptor activity; phosphatidylinositol bisphosphate binding
Biological process: heart development
Cellular component: cytoplasm; plasma membrane; mitochondrial envelope
Genetic constraint (gnomAD): Loss-of-function variants: 40 observed, 50.49 expected, observed/expected ratio (o/e) 0.79, 90% interval 0.61 to 1.03. The upper end of that interval is the gene's LOEUF score, 1.03, which puts it in group 4 of 6, group 1 being the genes least tolerant of losing a copy. Missense variants: 425 observed, 470.81 expected, observed/expected ratio (o/e) 0.9, 90% interval 0.83 to 0.98. Synonymous variants: 175 observed, 180.88 expected, observed/expected ratio (o/e) 0.97, 90% interval 0.86 to 1.1.
Homologues: Orthologues: chimpanzee ADAP2 (99% identical), dog ADAP2 (89% identical), pig ADAP2 (89% identical), rabbit ADAP2 (87% identical), mouse Adap2 (85% identical), rat Adap2 (83% identical), guinea pig ADAP2 (81% identical), macaque ADAP2 (73% identical), tropical clawed frog adap2 (60% identical), zebrafish adap2 (57% identical). Paralogues in human: ADAP1 (56% identical), ARAP1 (26% identical), ARAP2 (25% identical), ARAP3 (24% identical), SMAP1 (23% identical), SMAP2 (22% identical), ASAP2 (21% identical), AGAP2 (19% identical), AGAP3 (19% identical), ASAP1 (19% identical), ACAP2 (18% identical), ACAP3 (18% identical), and 16 more.
Diseases named in the same sentence as ADAP2 in open-access papers:
ADAP2 is named in the same sentence as 17 diseases in open-access papers, as found by Europe PMC text mining. Sharing a sentence is not in itself a finding about the gene and the disease. The quoted sentences say what the papers report.
neurofibroma (4 papers, 2012 to 2024). An intraneural or extraneural neoplasm arising from nerve tissues and neural sheaths. "The cancer-recurrent pattern for an LCP is exemplified in the EVI2/ADAP2 17q11.2 locus, which is associated with Neurofibromatosis type 1 microdeletion syndrome, a severe phenotype with overgrowth and increased neurofibromas." (PMID 30767760, 2019). "Interestingly CENTA2 gene, alias ADAP2, was found to be expressed in neurofibromas and it has been candidate as a modifier gene contributing to a neurofibroma aberrant growth, both in number and in size, detected in NF1 microdeletion patients carrying a CENTA2 constitutional deletion." (PMID 23285209, 2012). "Also, ADAP2 is able to regulate type 1 interferon (IFN1) response during viral infection, a signalling pathway that might contribute to neurofibroma formation." (PMID 38448973, 2024). "These rearrangements lead to a more severe “contiguous gene syndrome” with higher incidence of neurofibromas and MPNSTs, likely attributable to the involvement of tumor suppressor genes in co-deleted regions (e.g., SUZ12—OMIM *606245, RNF135—OMIM *611358, and ADAP2—OMIM *608635)." (PMID 33919865, 2021).
viral infection (2 papers, 2021 to 2024). "Similarly, CNOT7 and ADAP2, both down-regulated in severe malaria, were previously reported to have a protective role during viral infections." (PMID 34746025, 2021).
cervical cancer (1 paper, 2021). A primary or metastatic malignant neoplasm involving the cervix. "ADAP2 downregulation has been reported to promote cervical cancer HeLa cell proliferation." (PMID 34856991, 2021).
glioma (1 paper, 2020). A benign or malignant brain and spinal cord tumor that arises from glial cells (astrocytes, oligodendrocytes, ependymal cells). "The mRNA expression of APOBEC3C, FCGRT, GNG5, and SP100 was elevated in glioma, whereas the expression of ADAP2, ALOX5AP, and LRRC25 was low." (PMID 32431729, 2020).
Hyperkeratosis (1 paper, 2021). Hyperkeratosis is a histopathological term defining a thickened stratum corneum and may be present in many different skin conditions, with many possible overlaps. "The overlapping DEGs included genes associated with hyperkeratosis (upregulated LCE3E and TMEM45A), wound healing (upregulated KRT17, IL36G, TNC, and TGFBI), barrier defects (downregulated FRAS1 and BCL11A), and response to infection (upregulated IL36G, ADAP2, DFNA5, RFTN1, LITAF, and TMEM173)." (PMID 34506598, 2021).
multiple sclerosis (1 paper, 2015). A progressive autoimmune disorder affecting the central nervous system resulting in demyelination. "Indeed, ADAP2 has been shown to be upregulated by IFN treatment in various human cells, such as primary hepatocytes and PBMCs isolated from multiple sclerosis patients undergoing IFN treatments." (PMID 26372645, 2015).
infection (4 papers, 2015 to 2021). The state of being infected such as from the introduction of a foreign agent such as serum, vaccine, antigenic substance or organism. "The ADAP2 expression is upregulated by type I interferons, and an ADAP2 overexpression restricts infection by dengue virus (DENV) and vesicular stomatitis virus (VSV) via a mechanism that requires intact Arf6 GAP activity." (PMID 31060328, 2019). "We also found that ADAP2 expression restricted DENV infection across a variety of multiplicity of infections (MOIs)." (PMID 26372645, 2015). "If ADAP2 restricts DENV entry, we would expect that exposure of ADAP2-expressing cells to light early in infection (2hrs p.i.), would elicit a greater inhibition of DENV infection than when cells are infected under non-illuminated conditions." (PMID 26372645, 2015). "In addition, several DEGs, including IL36G, ADAP2, DFNA5, RFTN1, LITAF, and TMEM173, that were commonly upregulated in the partial sets of the epithelium and mucosa are associated with the response to infection." (PMID 34506598, 2021). "While the expression of ADAP2 and GILT did not inhibit HCoV-OC43pp infection, expression of LY6E in Flp-In TREx 293 cells efficiently suppressed the infection of lentiviral particles pseudotyped with the envelope glycoproteins of all the human CoVs, except for SARSpp." (PMID 32641482, 2020).
tumor (2 papers, 2021 to 2022). "Of note, MKI67 monocytes and APOE macrophages were mainly derived from tumor, while ADAP2 and MARCO macrophages were mainly from ascites." (PMID 36248860, 2022). "Haploinsufficiency of certain genes may contribute to dysmorphic facial features, overgrowth and reduced cognitive capability (RNF135) or heart defects (ADAP2), whereas others might have tumor suppressive function, thus their deletion promote tumor development (SUZ12, ATAD5)." (PMID 34168676, 2021).
cancer (1 paper, 2019). A tumor composed of atypical neoplastic, often pleomorphic cells that invade other tissues. "Of the 9 coding genes and one other lncRNA in this locus, expression of AC138207.5 is significantly correlated with ADAP2 in all five cancer types, and with EVI2A/B in most of the five cancer types." (PMID 30767760, 2019).
ADAP2 also shares sentences with these, for which no sentence is quoted: cardiac diseases (1 paper); cognitive defects (1); developmental delay (1); intellectual disabilities (1); malaria (1); metabolic disease (1); microdeletion syndrome (1); neurofibromatosis type 1 (1).